EDN1 (endothelin 1)
Diseases named in the same sentence as EDN1 in open-access papers (continued):
Sharing a sentence is not in itself a finding about the gene and the disease.
atherosclerosis (200 papers, 2004 to 2026). A disease characterized by the build-up of fatty material and calcium deposition in the arterial wall resulting in partial or complete occlusion of the arterial lumen. "Another mechanism mediated by resveratrol on endothelial cells is the downregulation of endothelin-1 (ET-1), a potent vasoconstrictor implicated in the development of vascular disease and atherosclerosis." (PMID 38562461, 2024). "Some studies have suggested an association between the EDN1 polymorphism and risk of atherosclerosis progression in great cardiac vessels and coronary arteries." (PMID 36046789, 2022). "Higher levels of endothelin-1 (ET-1) are associated with atherosclerosis, while there is also evidence concerning the ET-1-induced enzymatic destruction of articular cartilage." (PMID 34685552, 2021). "Increased transcript levels of markers associated with atherosclerosis or cardiovascular impairments (Edn1, Selp, Alox5, and Icam1) further indicate plausible detrimental effects of CNP exposure on aortic tissue at 24 h post inhalation." (PMID 28637465, 2017). "Endothelin-1 mediates activation of vascular smooth muscle cells (VSMC) and showed increased expression in human atherosclerotic lesions, indicating that endothelin-1 contributes to the pathogenesis of chronic inflammation associated with atherosclerosis." (PMID 26488411, 2015). "To understand the vascular function of our study population, we assessed endothelin-1, a potent vasoconstrictor, and plasminogen activator inhibitor 1, an important risk factor for thrombosis and atherosclerosis." (PMID 26289439, 2015). "Endothelin-1 is also an important regulator of vascular tone and has been implicated in the pathogenesis of atherosclerosis." (PMID 24571954, 2014). "The potent endothelium-derived vasoactive factor endothelin-1 (ET-1) has been implicated in the pathophysiology of atherosclerosis and its complications." (PMID 17374166, 2007). "Increased aortic stiffness (AS) is a recognized predictor of cardiovascular morbidity and mortality in patients with chronic kidney disease (CKD), and endothelin-1 (ET-1), a potent vasoconstrictor, has been associated with vascular dysfunction and atherosclerosis." (PMID 41820016, 2026). "One of the most important conditions in which endothelin-1 is implicated is atherosclerosis." (PMID 41153763, 2025). "Therefore, A group of associated atherosclerosis genes was regulated, endothelin 1 (EDN1), angiotensin II (ANGII), as well as thromboxane A2 (TxA2) downregulated and endothelial nitric oxide synthase (eNOS), prostacyclin (PGI2), and VEGF upregulated." (PMID 32266263, 2020). "Additionally it has been demonstrated that diabetic women have an increase in endothelin-1 and oxidative stress, known factors related to enhanced atherosclerosis and thrombotic risk." (PMID 30881344, 2019). "Interleukin 18 (IL-18), fetuin-A, soluble intercellular adhesion molecule-1 (sICAM-1), and endothelin-1 (ET-1) are a group of cytokines and adhesion molecules which activate and deregulate endothelial function, and could increase the risk of atherosclerosis." (PMID 27527149, 2016). "The occurrence of atherosclerosis in older adults is closely related to the regulation of endothelin-1(ET-1), nitric oxide (NO) and angiotensin II levels by vascular endothelial cells." (PMID 39325934, 2024). "Endothelial cells senescence contributes to atherosclerosis by regulating the levels of endothelin-1 (ET-1), monocyte chemoattractant protein-1 (MCP-1), angiotensin II, and nitric oxide (NO)." (PMID 37974282, 2023). "Endothelin-1 can also accelerate the progression of atherosclerosis via upregulation of the mitogen-activated protein kinase pathway." (PMID 37760823, 2023). "EGCG reduces production of endothelin-1 (ET-1) which acts as a potent vasoconstrictor but also increases a lipid biosynthesis and accelerates the progression of atherosclerosis." (PMID 36613784, 2022).
atherosclerosis (continued). "The expression levels of hs-CRP, TNF-α, NO and EDN1, PTGIS, and AGT genes at risk of atherosclerosis were significantly decreased." (PMID 36180828, 2022). "Subsequently, genes related to the atherosclerosis indicators EDN1, PTGIS, AGT, NOS3, ICAM1, and VCAM1 were detected by qPCR." (PMID 36180828, 2022). "Reports have indicated that endothelin-1 (ET-1) overexpression in ECs promotes atherosclerosis progression through NOX1 in type 1 diabetes, perivascular oxidative stress, and inflammation." (PMID 36389728, 2022). "TMAO is also reported to promote the release of a range of inflammatory factors, e.g., interleukin-8 (IL-8) and endothelin-1 (ET-1), which can lead to vascular endothelial damage and resulting atherosclerosis." (PMID 36420057, 2022). "Studies have also shown that IR stimulates the production of endothelin-1 and then further promotes the increasing of vasoconstrictive tension and the progression of atherosclerosis." (PMID 34869637, 2021). "Senescent endothelial cells show increased endothelin-1 (ET-1) release and reduced nitric oxide (NO) production, which elevate local inflammation, induce atherosclerosis and damage vascular integrity." (PMID 34366891, 2021). "C-terminal endothelin-1 (CT-proET-1) is a precursor of endothelin-1 (ET-1), a peptide with vasoconstrictive properties playing a role in the pathogenesis of atherosclerosis and peripheral endothelial dysfunction." (PMID 33504164, 2021). "Endothelin-1 (ET-1) and its associated G-protein coupled receptors ETAR and ETBR are involved in the pathogenesis of atherosclerosis." (PMID 33255872, 2020). "During atherosclerosis progression, the increase in the expression of endothelin-1 (ET-1) is accompanied by proliferation, migration, and contraction of VSMCs, which are involved in matrix remodeling and synthesis of the extracellular matrix." (PMID 33339328, 2020). "Cardiovascular disease mainly referred to two signaling pathways of kidney-tonifying herbal medicines including atherosclerosis signaling and endothelin-1 signaling." (PMID 28031022, 2016). "The significant pathways in cardiovascular related signaling included atherosclerosis signaling and endothelin-1 signaling, which was more significant in kidney Yin-tonifying herbal medicines." (PMID 28031022, 2016). "Several studies have confirmed that endothelin-1(ET-1) plays an important role in the process of atherosclerosis formation." (PMID 26565974, 2015). "Endothelin-1 (ET-1) is a potent vasoconstrictive peptide and mitogen that plays multiple roles in the progression of atherosclerosis, vascular inflammation and remodeling." (PMID 22931291, 2012). "Endothelin-1 (EDN1) is a potent vasoconstrictor that activates signaling pathways leading to atherosclerosis." (PMID 20308035, 2010). "Additionally, elevated calcium levels can enhance the synthesis of endothelin-1 (ET-1), a key mediator in the development of atherosclerosis and acute coronary syndromes (ACSs)." (PMID 40648911, 2025). "For example, CRP reduces endothelial nitric oxide synthase (eNOS) activity which subsequently reduces vasodilator effects of NO and increases vasoconstrictor effects of Endothelin-1 (ET-1) all of which increases the chances of atherosclerosis and clot formation." (PMID 35192097, 2023). "On the other hand, glucocorticoids regulate vasoconstrictors such as endothelin-1 and angiotensin-II, promoting vasoconstriction through an increase in endothelin-1 production and activation of angiotensin-II signaling, with notable impacts on atherosclerosis and endothelial cell dysfunction." (PMID 38017255, 2023). "There are many key molecules involved in the laminar shear stress and atherosclerosis pathways, such as endothelin 1 (EDN1), vascular cell adhesion molecule 1 (VCAM1), KLF2, intercellular adhesion molecule 1 (ICAM1), and platelet and endothelial cell adhesion molecule 1 (PECAM1)." (PMID 36364780, 2022).
atherosclerosis (continued). "Atherosclerosis-induced hypercholesterolemia is a cardiovascular progression coupled with type 2 diabetes mellitus, which increases reactive oxygen species (ROS), and subsequent eNOS degradation, releasing endothelin 1-induced vasoconstriction." (PMID 36297290, 2022). "In addition, ATRA can inhibit the expression of endothelin-1 (ET-1) mRNA in endothelin-1 (ET-1) mRNA in endothelial cells (ECs), leading to anti-atherosclerosis effects." (PMID 35883425, 2022). "High levels of triglycerides can induce inflammation and oxidative stress to enhance adhesion molecule expression and foam cell formation, to stimulate the toxicity of smooth muscle and to increase the release of endothelin-1 responsible for the development of atherosclerosis." (PMID 35566636, 2022). "In addition, it was established that the KED peptide has contributed to the endothelial cell growth factor (VEGF) recovery and endothelin-1 expression in the aortic endothelial cell culture received from patients with atherosclerosis." (PMID 34071923, 2021). "Therefore, by suppressing oxLDL-induced endothelin-1 (ET-1) expression, miRNA-125a-5p plays a protective role against the development of atherosclerosis." (PMID 35011660, 2021). "Our data demonstrated that EDN1 rs5370 polymorphism is related to increased risk of LAS development regardless of other atherosclerosis risk factors." (PMID 29849817, 2018). "Our ex vivo aortic ring assay result showed that BAY61 prevented sprouting of VSMCs, and furthermore, suppression of Syk has been suggested to be an effective way to control atherosclerosis via subsequent suppression of endothelin-1 production from endothelial cells." (PMID 28100269, 2017). "The potent vasoconstrictor endothelin-1 (ET-l) secreted from vascular endothelial cells significantly elevated in the SiO2NPs, Al2O3NPs, or ZnONPs administered to rats which may be attributed to atherosclerosis, endothelial injury, and heart failure." (PMID 36942197, 2023). "chymase has an important role in angiogenesis during tumor progression, MMP activation in atherosclerosis, TGF-ß activation and endothelin-1 formation." (PMID 39859396, 2025). "The impact of GIP on calcium signaling pathways, leading to the production of endothelin-1 (ET-1) and osteopontin (OPN), requires further investigation to understand its influence on endothelial cell function and atherosclerosis development." (PMID 39493783, 2024). "AGEs enhance vasoconstriction (by increasing endothelin-1 levels), reduce vasodilation (by decreasing NO levels) and stimulate AGE-modification of extracellular matrix to accelerate the progression of atherosclerosis." (PMID 31963378, 2020). "Endothelin-1 is a prognostic indicator for cardiovascular diseases and is elevated in atherosclerosis due to the increased expression of endothelin converting enzyme (ECE) in plaques, which accelerates conversion of the precursor big ET-1 to ET-1." (PMID 23840332, 2013). "Because EDN1 also possesses mitogenic properties, it plays a role in regulating the proliferation of intimal smooth muscle cells and inducing IMT in atherosclerosis." (PMID 24174980, 2013). "This is compounded by excess endothelin-1 (ET-1), a potent vasoconstrictor overproduced in MASLD under proinflammatory and oxidative conditions, promoting vascular smooth muscle proliferation and atherosclerosis." (PMID 40869400, 2025). "Endothelin-1 (ET-1) levels are altered in atherosclerosis, while the roles of the endothelin receptors ETAR and ETBR during the pathogenesis of atherosclerosis remain unclear." (PMID 40076930, 2025). "Endothelin-1 (ET-1), advanced glycation end products (AGEs), receptor for AGEs (RAGE), and cyclooxygenase-2 (COX-2) are also considered to contribute to the progression of atherosclerosis." (PMID 38542060, 2024).
atherosclerosis (continued). "Upregulation of EDN1 (ET1) is critically involved in inflammation/vasoconstriction, and the very early stage of plaque evolution, whereas increased secretion of ET1 has also been reported to accelerate the pathogenesis of atherosclerosis." (PMID 36364780, 2022). "Growth factors [transforming growth factor-β (TGF-β), epidermal growth factor (EGF), endothelin-1 (ET-1)] stimulate proteoglycan synthesis resulting in retention and accumulation of low density lipoprotein (LDL) in vesselintima and leading to atherosclerosis development." (PMID 34837677, 2021). "Endothelin (predominantly endothelin-1, ET-1) via its receptors (ETA and/or ETB) triggers vasoconstriction (both systemic as well as pulmonary), promotes inflammation, oxidative damage, fibrinogenesis, and atherosclerosis, and is involved in salt and water regulation." (PMID 25893478, 2015). "Several signaling pathways are involved in the progression of atherosclerosis and restenosis and the key players include peroxisome proliferators-activated receptor gamma (PPARγ), platelet-derived growth factors (PDGF), endothelin-1 (ET-1), thrombin, fibroblast growth factor (FGF)." (PMID 25302079, 2014). "Resistin has also been shown to have direct effects on endothelial cell activation by inducing the expression of endothelin-1 (ET-1) and the cell adhesion molecules VCAM-1 and ICAM-1, and resistin's secretion by the atherosclerotic macrophages could promote atherosclerosis in humans." (PMID 23484124, 2013).
diabetes (187 papers, 2004 to 2026). "Various single nucleotide polymorphisms (SNPs) in the EDN1 gene are related to microvascular complications of type 2 diabetes mellitus (T2DM) such as retinopathy, neuropathy and nephropathy." (PMID 38187330, 2024). "In fact, high endothelin-1 levels are associated with the impairment of vascular tone regulation in diabetes." (PMID 36142551, 2022). "Sirt1 deletion caused renal injury in diabetes through increasing the expressions of endothelin-1 and TGF-β131." (PMID 29700282, 2018). "Vascular endothelial growth factor (VEGF) and endothelin 1 (ET1) are important bioactive substances synthesized in endothelial cells and implicated in diabetic vascular complications." (PMID 28836407, 2017). "In the context of diabetes, endothelin-1 (ET-1) has been implicated in vasoconstriction, renal injury, mesangial proliferation, glomerulosclerosis, fibrosis and inflammation, largely through activation of its endothelin A (ETA) receptor." (PMID 26239552, 2015). "In diabetes, hyperglycaemia causes up-regulation of endothelin 1 (ET-1) and transforming growth factor beta 1 (TGF-β1)." (PMID 25753689, 2015). "The results of this study and others point to benefits for persons with diabetes mellitus with relationship to the risks associated with dysfunction of the lipid profile such as: macrovascular complications, endothelin-1, coronary heart disease and oxidative stress." (PMID 18477407, 2008). "Moreover, persistently elevated plasma endothelin-1 levels, reduced eNOS activity and NO production are linked to the development of cardiac fibrosis and diastolic dysfunction in diabetic patients and diabetes-induced cardiac fibrosis is prevented by endothelial cell-specific endothelin-1 knockout." (PMID 35204091, 2022). "This study aimed to explore the association between plasma big endothelin‐1 (ET‐1) and major adverse cardiovascular events (MACE) in CAD patients who underwent PCI with a focus on the influence of kidney function and diabetes status in secondary prevention." (PMID 40692280, 2025). "Endothelin-1 is also involved in the pathology of diabetes, as studies on mice proved that peptide endothelin ET-1 traps have a significant therapeutic effect." (PMID 36832168, 2023). "Diabetes also increases vascular levels of advanced glycation end products (AGEs) and endothelin-1 (ET-1)." (PMID 36830898, 2023). "Endothelin-1 is well investigated, is elevated in patients with diabetes, and is related to muscle cellular senescence and fibrosis." (PMID 35468098, 2022). "Interaction between big endothelin-1 and diabetes in the prognosis of MACEs and secondary end points." (PMID 35694656, 2022). "Proinflammatory microglial activation and cognitive aggravation were reported not only in an MCAO model but also in an endothelin-1 (ET-1) injection model with diabetes mimicking conditions via the infusion of a high glucose solution." (PMID 36142661, 2022). "In patients with diabetes, NF-κB was also responsible for increased levels of endothelin-1 (ET-1), one of the most potent vasoconstrictors known." (PMID 36686462, 2022). "Excessive endothelin 1 (ET-1) produced during diabetes further damages heart cells, resulting in weak cardiac contractility." (PMID 34305595, 2021). "As an alternative target, endothelin-1 (ET-1) is upregulated in the retina in diabetes and has dual deleterious action on microvessels and neurons." (PMID 30030554, 2018). "Experimental evidence suggests that endothelin 1 (ET-1) is involved in the development of retinal microvascular abnormalities induced by diabetes." (PMID 30428543, 2018). "Diabetes-induced vascular endothelial dysfunction can reduce NO production and elevate endothelin-1 (ET-1) levels, diminishing capillary diameter and restricting blood flow." (PMID 29082239, 2017). "The production and plasma levels of endothelin-1 are elevated in patients with diabetes, and a positive correlation between plasma endothelin-1 levels and diabetic microangiopathy has been described." (PMID 27095564, 2016).